EXO5 (exonuclease 5)
Description:
Single-stranded DNA (ssDNA) bidirectional exonuclease involved in DNA repair. Probably involved in DNA repair following ultraviolet (UV) irradiation and interstrand cross-links (ICLs) damage. Has both 5'-3' and 3'-5' exonuclease activities with a strong preference for 5'-ends. Acts as a sliding exonuclease that loads at ssDNA ends and then slides along the ssDNA prior to cutting; however the sliding and the 3'-5' exonuclease activities are abolished upon binding to the replication protein A (RPA) complex that enforces 5'-directionality activity.
Synonyms: Exo V; hExo5; C1orf176; DEM1; FLJ21144
Tractability: Small molecule: a structure with a bound ligand is known. PROTAC: ubiquitination databases record sites on it.
Gene: Protein-coding gene on chromosome 1 (40,508,441 to 40,517,724, forward strand). Ensembl gene ENSG00000164002.
Subcellular location: Nucleus; Cytoplasm, cytosol
Subcellular location (Human Protein Atlas): Nucleoplasm; Cytosol; Nuclear speckles
Gene Ontology:
Molecular function: 4 iron, 4 sulfur cluster binding; single-stranded DNA 5'-3' DNA exonuclease activity; single-stranded DNA 3'-5' DNA exonuclease activity
Biological process: interstrand cross-link repair
Cellular component: cytosol; nuclear speck; nucleoplasm; nucleus
Genetic constraint (gnomAD): Loss-of-function variants: 19 observed, 26.56 expected, observed/expected ratio (o/e) 0.72, 90% interval 0.5 to 1.05. The upper end of that interval is the gene's LOEUF score, 1.05, which puts it in group 4 of 6, group 1 being the genes least tolerant of losing a copy. Missense variants: 364 observed, 458.33 expected, observed/expected ratio (o/e) 0.79, 90% interval 0.73 to 0.87. Synonymous variants: 147 observed, 176.05 expected, observed/expected ratio (o/e) 0.83, 90% interval 0.73 to 0.96.
Homologues: Orthologues: chimpanzee EXO5 (98% identical), macaque EXO5 (97% identical), guinea pig EXO5 (85% identical), dog EXO5 (84% identical), mouse Exo5 (84% identical), rabbit EXO5 (83% identical), pig EXO5 (83% identical), rat Exo5 (82% identical), zebrafish exo5 (40% identical).
Diseases named in the same sentence as EXO5 in open-access papers:
EXO5 is named in the same sentence as 3 diseases in open-access papers, as found by Europe PMC text mining. Sharing a sentence is not in itself a finding about the gene and the disease. The quoted sentences say what the papers report.
cancer (3 papers, 2021 to 2025). A tumor composed of atypical neoplastic, often pleomorphic cells that invade other tissues. "Although the roleof EXO5 in cancer appears to be important forboth tumor initiation and progression, comprehensive structural studiesremain lacking." (PMID 40115981, 2025).
EXO5 also shares sentences with these, for which no sentence is quoted: Bloom syndrome (1 paper); cervical cancer (1).